PTH (parathyroid hormone)
Diseases named in the same sentence as PTH in open-access papers (continued):
Sharing a sentence is not in itself a finding about the gene and the disease.
Hypocalcemia (continued). "Furthermore, the literature shows that preoperative low or low-normal levels of PTH are significantly associated with hypocalcemia post-surgery." (PMID 38646308, 2024). "Clinicians should be aware that a history of thyroid surgery combined with viral infections, including COVID-19, may increase the risk of hypocalcemia, even when PTH levels are normal." (PMID 39262524, 2024). "ROC curve analysis also showed statistically significant associations between the occurrence of laboratory-verified hypocalcemia on the fifth postoperative day and the values of PTH and serum calcium sampled one hour after surgery and on the first postoperative day." (PMID 38322433, 2024). "Patients with Mg deficiency may present hypocalcemia in spite of high PTH levels, suggesting resistance to PTH action in bone and kidney." (PMID 36986033, 2023). "PTH serum concentrations could be used as a predictive factor of risk of development of post‐surgical hypocalcemia in dogs with primary hyperparathyroidism." (PMID 38053473, 2023). "Therefore, further prospective studies should investigate the prognostic value of hypocalcemia in association with serum 25-hydroxyvitamin D [25(OH)D], parathyroid hormone (PTH) and blood gas levels." (PMID 37371636, 2023). "This procedure (that allows fetal lung development) increases urinary calcium loss and might cause hypocalcemia due to magnesium-induced parathormone (PTH) suppression, thus potentially causing reduced BMD." (PMID 37175006, 2023). "In addition, patients on MHD had associated HTN, hypocalcemia, hyperphosphatemia, high calcium–phosphate product, parathyroid hormone, arterial stiffness, and ED." (PMID 38276267, 2023). "As for our patients with the homozygous P1 mutation, hypocalcemia due to the mutant PTH could have led to the diagnosis of either hypoparathyroidism or PHP, depending on the assay used for PTH measurement." (PMID 36795755, 2023). "There is actually claim about the use of serum P as first-step examination in the diagnostic workup of bone mineral diseases and the missed use of diagnostic tests (e.g., serum PTH measurement and definition of hypocalcemia), resulting in frequent underdiagnoses." (PMID 37854194, 2023). "Pseudohypoparathyroidism type 1 (PHP1) is a disease caused by parathyroid hormone (PTH) resistance featuring hypocalcemia, elevated PTH level, unelevated urinary cyclic adenosine monophosphate (cAMP) after exogenous PTH injection, with/without Albright's hereditary osteodystrophy (AHO)." (PMID 38017461, 2023). "Therefore, in our prospective interventional study, we have investigated the association between postoperative 4 h PTH and vitamin D with postoperative symptomatic and biochemical hypocalcemia in patients undergoing total and near total thyroidectomy." (PMID 37636752, 2023). "However, parathyroid hyperplasia was not caused by enhanced intracellular accumulation of the mutant pro[P1]PTH, as in dominant variants of hypoparathyroidism but because of hypocalcemia and consequently insufficient activation of the CaSR." (PMID 36795755, 2023). "Additionally, ioPTH 3, relative ioPTH decline, and PTH on POD 1 were significantly associated with postoperative hypocalcemia." (PMID 35813620, 2022). "In summary, hypoparathyroidism, PTH resistance, and vitamin D insufficiency could cause hypocalcemia in hypomagnesemia individuals." (PMID 36589976, 2022). "ESKD can lead to hypocalcemia and/or hyperphosphatemia, stimulating excessive PTH secretion, causing secondary hyperparathyroidism, further exacerbating calcium and phosphate imbalance, forming a vicious circle, causing metabolic bone disease and calcification of arteries and other tissues." (PMID 35166181, 2022). "A high pre-operative PTH concentration results in severe bone malnutrition and substantial calcium deposition in the bone following PTX, causing severe hypocalcemia, which at least in part explains the relationship between post-operative calcium concentration and PTH." (PMID 36531501, 2022).
Hypocalcemia (continued). "Hypocalcemia causes the release of parathyroid hormone, which raises the blood calcium level." (PMID 35091933, 2022). "However, systemic ionized hypocalcemia among critically ill patients is multifactorial cause included abnormal parathyroid hormone secretion, vitamin D deficiency, transfusion of citrated, the effect of circulating catecholamines, and disease severity." (PMID 35110648, 2022). "PTH resistance causes elevated PTH levels, hypocalcemia, and hyperphosphatemia." (PMID 35626900, 2022). "Hypocalcemia is the most common complication after thyroidectomy, with variable incidence in literature (3–20%), associated with transient or definitive hypoparathyroidism (hypo-PTH)." (PMID 35565776, 2022). "Since early identification of patients at risk for symptomatic hypocalcemia is crucial, in this real-world study, we focused on the performance characteristics of PTH and calcium levels before surgery and at 10 min and 4 h post-surgery, as well as their pre/post-surgery ratios." (PMID 35566513, 2022). "Hypoparathyroidism is a syndrome of hypocalcemia and hyperphosphatemia caused by decreased PTH." (PMID 35937810, 2022). "Although the cause for this increased susceptibility to infections in HypoPT is unknown, hypocalcemia and low PTH levels may be involved." (PMID 36382753, 2022). "It is hypothesized that the body’s increased demand for calcium due to the stress of surgery combined with a baseline diminished reserve of parathyroid hormone is the cause of postoperative hypocalcemia." (PMID 36292790, 2022). "Sixteen patients (18.4%) had transient postoperative hypocalcemia (range 1.9–2.1), there was a positive relationship between the occurrence of hypocalcemia and vitamin D deficiency, and an inverse correlation between PTH concentration and postoperative hypocalcemia." (PMID 36268338, 2022). "Parathormone (PTH) and calcium levels, measured several hours after surgery, have been suggested as valuable markers for detecting patients at risk for post-thyroidectomy hypocalcemia." (PMID 35566513, 2022). "Part of the difficulty in normalizing serum PTH with vitamin D supplementation as CKD progresses results from the impact of prolonged hypocalcemia or vitamin D deficiency on parathyroid cell proliferation to meet the requirements for higher serum PTH to normalize serum calcium." (PMID 34950686, 2021). "Lowered basal levels of 1,25(OH)2D3 in M1‐IKO and M1/M21‐DIKO mice lead, in turn, to reduced intestinal absorption of Ca and P, which causes hypocalcemia and hypophosphatemia that promotes a rise in PTH and a reduction in FGF23 levels, and a broad Cyp27b1 null‐like skeletal phenotype." (PMID 33553989, 2021). "This may be the principal mechanism underlying both impaired PTH secretion and end-organ resistance to PTH, which together contribute to the development of hypocalcemia." (PMID 34416890, 2021). "In fact, hypomagnesemia, decreasing PTH secretion, induces peripheral PTH resistance and mimics/increases hypocalcemia symptoms (i.e., confusion or memory loss, muscle spasms, numbness and tingling in the hands, feet, and face, depression, hallucinations, etc.)." (PMID 34638612, 2021). "Initiating the correct supplementation depending on deficiency is important, as phosphate supplementation in the hypocalcaemic state will bind ionised calcium, exacerbating hypocalcaemia, driving PTH higher, exacerbating renal phosphate loss, and worsening MBPD." (PMID 33614549, 2021). "Defect in the activation of vitamin D in the kidneys due to chronic kidney disease (CKD) leads to hypocalcemia and hyperphosphatemia, resulting in a compensatory increase in parathyroid gland cellularity and parathyroid hormone production and causing secondary hyperparathyroidism (SHP)." (PMID 34408941, 2021).
Hypocalcemia (continued). "For those patients deemed to be at intermediate or high risk of developing hypocalcaemia (based on the PTH value), local guidelines advise on medical treatment and timing of further blood tests, namely repeated calcium monitoring at 12-hourly intervals and titrating up of calcium supplements." (PMID 34164240, 2021). "Barnhart described that prolonged use of phenytoin may cause side effects such as osteomalacia, hypocalcemia, hyperphosphatemia, and increased parathyroid hormone concentration." (PMID 34387971, 2021). "Defects in the processing of PTH may lead to hypoparathyroidism, resulting in hypocalcemia and numbness, which can cause psychiatric disorders." (PMID 34667146, 2021). "In the re-audit, two patients were identified to be at high risk of hypocalcaemia (PTH <0.6)." (PMID 34164240, 2021). "The measurement of serum parathormone (PTH) immediately after surgery is a sensitive and specific method for assessing the function of parathyroid glands while it can identify patients at risk of hypocalcaemia." (PMID 34909164, 2021). "Hypermagnesemia may cause hypocalcemia, through activation of calcium-sensing receptors in the parathyroid glands, thereby suppressing PTH secretion." (PMID 34416890, 2021). "Hyperphosphatemia, hypocalcemia, decreased calcium, and vitamin D receptor expression, 1,25-dihydroxyvitamin D3 deficiency, and parathyroid hormone (PTH) resistance may partly play a role in the secondary hyperparathyroidism pathogenesis." (PMID 33691727, 2021). "Conditions of chronic magnesium depletion (as may be seen in severely malnourished patients with AN) can cause hypocalcemia with inappropriately normal or overtly low PTH levels." (PMID 32219087, 2020). "The authors observed that vitamin D deficiency combined with hypocalcemia, hyperphosphatemia, and high PTH concentrations in septic foals may point to PTH resistance being associated with the development of these abnormalities." (PMID 32942601, 2020). "Previous studies hypothesized that patients with postoperative hypoparathyroidism whose preoperative vitamin D level was low were at increased risk for lower serum calcium levels and symptomatic hypocalcemia due to the loss of compensatory role of PTH." (PMID 32774362, 2020). "In addition, our study also revealed that hypocalcemia was associated with hypoproteinemia and imbalanced VD and PTH in the acute phase of COVID-19." (PMID 32589164, 2020). "Similarities between familial isolated hypoparathyroidism in humans and the refractory hypocalcemia observed in Thoroughbred foals led to the hypothesis that genetic variants in PTH, GCM2, CASR, GNA11 or TRPM6 may be responsible for the disease in the horse." (PMID 32986719, 2020). "Moreover, from this study, it emerged that preoperative vitamin D deficiency is more significant than a low PTH value in predicting postsurgical hypocalcemia." (PMID 33101410, 2020). "Reduced phosphate reabsorption may be the result of increased parathyroid hormone (PTH) levels due to hypocalcemia induced by vitamin D deficiency or magnesium deficiency due to phosphaturia." (PMID 32570709, 2020). "This is attributed to a combination of factors, including reduction in vitamin D synthesis, hyperphosphatemia, hypocalcemia, and PTH skeletal resistance which will eventually increase the risk of mortality and morbidity as a result of bone disease and fractures." (PMID 33180791, 2020). "As expected, VDD animals exhibited hypophosphatemia, hypocalcemia and increased plasma PTH concentration, since vitamin D deficiency diminishes calcium intestinal absorption, resulting in decreased calcium concentration and increased production of PTH." (PMID 31295336, 2019). "Moreover, in the patient with cherubism, hypocalcemia was associated with an inappropriately normal serum PTH concentration." (PMID 31687646, 2019).
Hypocalcemia (continued). "Therefore, the present study investigated, in a sample of the adult general population, the associations of serum calcidiol and serum calcitriol with hypocalcemia, high PTH, and other indices of mineral homeostasis." (PMID 31374914, 2019). "Alveolar bone resorption may be linked systemically to release of parathyroid hormone in response to hypocalcemia induced by hyperphosphatemia." (PMID 30754693, 2019). "Four hours after total thyroidectomy, there was a significant change of PTH level, which guide physicians as the valuable predictor of hypocalcemia for treatment of high-risk patients in order to decline the risk of post-operative hypocalcemia development and earlier hospital discharge." (PMID 30989072, 2019). "Findings for calcidiol deficiency and hypocalcemia or high PTH were similar using other datasets." (PMID 31374914, 2019). "Therefore, it is not possible to dissect the effects that direct loss of vitamin D signalling has from those of elevated PTH and hypocalcaemia on cardiac function in global VDR knockout mice kept on a normal diet." (PMID 30273386, 2018). "Animal studies have suggested that bone resistance to PTH contributes in hypocalcemia in Mg deficiency and studies in isolated perfused bone have revealed that Mg depletion reduces production of cyclic adenosine monophosphate (AMP) in bone with high levels of PTH." (PMID 29610664, 2018). "However, we suggest that patients with levels of intact PTH (iPTH) above the upper normal limit of the assay are first evaluated for hyperphosphataemia, hypocalcaemia, and vitamin D deficiency (2C)." (PMID 30236082, 2018). "Furthermore, rising PTH levels or above the upper limit should be evaluated for hypocalcemia or vitamin D deficiency." (PMID 29581540, 2018). "People with poor Mg intake may have hypocalcemia because of deficient Parathyroid Hormone (PTH) secretion and PTH end-organ resistance, as well as a higher risk for osteoporosis." (PMID 30097589, 2018). "Highlights SBEM: The use of perioperative PTH values may be useful in predicting the risk of hypocalcemia in patients undergoing thyroidectomy." (PMID 29694629, 2018). "Moreover, parenteral Mg stimulate PTH secretion, and it is therefore suggested that reduced PTH secretion is a key contributor to hypocalcemia in Mg deficiency." (PMID 29610664, 2018). "Vitamin D insufficiency may result in a relative hypocalcemia and high serum PTH concentrations, which alone has been linked to poor health outcomes." (PMID 29721404, 2018). "Thus, conditions of chronic magnesium depletion (chronic diarrhea, alcoholism, poorly controlled diabetes mellitus, and chronic use of proton pump inhibitors and diuretics) cause hypocalcemia with inappropriately normal or overtly low PTH levels." (PMID 29694629, 2018). "Besides hyperphosphatemia, proximal tubule resistance to PTH leads to decreased 1,25-dihydroxyvitamin D production, thus causing hypocalcemia." (PMID 27425121, 2017). "ADH2 may cause symptomatic hypocalcemia with low circulating parathyroid hormone (PTH) concentrations." (PMID 28194447, 2017). "In our study, the high-phosphate and low-calcium diet might have caused hypocalcaemia and augmented the increase of plasma PTH levels, leading to higher 1,25(OH)2D levels." (PMID 28094278, 2017). "However, in cases of increased demand for PTH, which occurs in hypocalcaemia such as that caused by renal failure, excessive proliferation of the parathyroid cells takes place (τ−1 increases)." (PMID 28652282, 2017). "Magnesium is needed for the secretion of PTH by the parathyroid glands and its depletion or excess may cause hypoparathyroidism and subsequent hypocalcemia." (PMID 28138323, 2016). "Accordingly, insufficient levels of PTH can cause hypocalcemia." (PMID 27857062, 2016).
Hypocalcemia (continued). "HBS is a complication of parathyroid surgery in which the correction of PHP is associated with rapid bone remineralization after surgery, causing profound and prolonged hypocalcemia which is exacerbated with suppressed PTH and associated with hypophosphatemia and hypomagnesemia." (PMID 27737322, 2016). "In humans, severe Mg deficiency impairs PTH secretion, causing hypocalcemia." (PMID 27136580, 2016). "Our initial hypothesis was that this rapid development of hypocalcemia in a model of total nephrectomy was caused by accumulation of C-terminal PTH fragments and/or of CT." (PMID 25885328, 2015). "Hypocalcemia and hyperphosphatemia together with decreased 1,25(OH)2D3 but increased PTH concentrations in septic foals indicates that PTH resistance may be associated with the development of these abnormalities." (PMID 26046642, 2015). "Magnesium levels after parathyroidectomy may decrease secondary to increased bone mineralization, causing a lower PTH secretion and a relative tissue specific resistance, increasing risk of severe hypocalcemia." (PMID 26640724, 2015). "Traditionally, hypocalcemia in uremia is explained by the associated decreased renal biosynthesis of calcitriol, P retention, decreased intestinal Ca absorption, and skeletal resistance to PTH, factors that all take time to respond." (PMID 25885328, 2015). "Meta‐analysis results are important here to inform whether PTH can suitably identify those at high risk of hypocalcaemia (to ensure they remain in hospital) and those at low risk of hypocalcaemia (who may therefore benefit from early hospital discharge)." (PMID 25800943, 2015). "Common causes include hypocalcemia with high parathyroid hormone (PTH), chronic kidney disease, vitamin D deficiency, hypocalcemia with low PTH, hypoparathyroidism, deregulation of PTH, acute pancreatitis, severe hypo-magnesemia due to suppression of PTH release, sepsis or severe illness." (PMID 26543729, 2015). "This is important because PTH could be elevated in states of vitamin D deficiency and hypocalcemia, while 24,25-dihyroxyvitamin D could be elevated in states on increased vitamin D degradation." (PMID 24992465, 2014). "These authors also speculated that the muscle impairment of osteomalacia might depend on associated metabolic changes such as hypocalcemia, hypophosphatemia, and elevated PTH levels." (PMID 25161666, 2014). "Therefore, we have raised the PTH cut-off level from 9 to 12 pg/ml in the development of a protocol for the of a single 1-hour PTH level in predicting the risk of development of hypocalcemia." (PMID 24476535, 2014). "We postulated that perhaps patients with low qPTH (i.e., PTH < 1.5 pmol/L) might have been more susceptible to hypocalcemia when the 25-OHD was low than when 25-OHD was normal." (PMID 22968355, 2013). "Reduced functions of PTH and/or vitamin D cause hypocalcemia." (PMID 23710380, 2013). "Among the various significant factors such as Graves’/toxic MNG, duration of the operation, number of parathyroid glands seen, parathyroid autotransplantation, preoperative Ca, and PTH-SC, only the latter two turned out to be independent factors associated with clinically relevant hypocalcemia." (PMID 22399155, 2012). "The study first analyzed potential risk factors and biochemical indicators associated with hypocalcemia and then compared the sensitivity, specificity, and predictability of PTH-SC with other biochemical variables or criteria such as serial Ca monitoring and following-morning PTH level (PTH-D1)." (PMID 22399155, 2012). "Intact parathyroid hormone levels are highly sensitive and specific for risk of hypocalcemia." (PMID 23108824, 2012). "Observed specificity levels were 78.5% (4-hour PTH), 87.3% (12-hour PTH), and 77.2% (sPTH), showing that tests can be used safely to determine which patients are at a low risk of developing symptomatic hypocalcemia when their postoperative i-PTH levels are normal." (PMID 23108824, 2012).